CXCR4 (C-X-C motif chemokine receptor 4)
Diseases named in the same sentence as CXCR4 in open-access papers (continued):
Sharing a sentence is not in itself a finding about the gene and the disease.
tumor (continued). "In order to further explore the mechanism behind the lack of differences in the behavior of the targeted-MB in the tumor models used, we validated CXCR4 expression in the same tumor models with [18F]MCFB, a CXCR4-targeting small-molecule analogue PET imaging agent previously developed by our group." (PMID 34793563, 2021). "These revealed that tumour cell differentiating towards Schwann‐like cell might occur and CXCR4 might encourage transversion of Schwann‐like cell differentiation in PNI of SACC." (PMID 34170080, 2021). "Inhibition of CXCR4 or Hedgehog (Hh) gene activity during tumor growth under hypoxic conditions reduced the size of the primary tumor and additionally reduced lymphatic metastasis to levels that were below those seen in control mice that were exposed to normoxic conditions." (PMID 34833360, 2021). "CXCR4 overexpression significantly promoted tumor growth of HCC in mice." (PMID 34555268, 2021). "The binding of CXCL12 to CXCR4 or ACKR3 on tumour cells has contrasting effects." (PMID 33803414, 2021). "Finally, we constructed a tumor xenograft model to determine the influence of CXCR4 overexpression on tumor growth of HCC." (PMID 34555268, 2021). "Nevertheless, our data suggests that a noticeable CXCR4-positive immune or epithelial cell population might accumulate in tumors and we have been able to demonstrate a major fraction of tumor cells to be CXCR4-positive." (PMID 33579381, 2021). "CXCR4 expression was reported to be mediated by several signaling mechanisms including protein kinase B (Akt) signaling that is known to modulate behavioral phenotypes in tumor such as anti-apoptosis, drug resistance and metastasis." (PMID 34220311, 2021). "Taken together with the reports that IL-11 binds to its receptors on osteoclasts or their precursors to regulate the formation and function of osteoclasts, these findings suggest that the Ac-KLF5/CXCR4 axis in tumor cells induces osteoclast differentiation by increasing IL-11 secretion." (PMID 33731701, 2021). "However, there is a large amount of evidence showing that increased CXCR4 expression on cell surface can promote tumor tropism in vivo, and efforts were also made in the current study to minimize animal suffering and to reduce the number of animals used." (PMID 34068264, 2021). "Altogether, the high expression levels of CD133 and CXCR4 could be explained by the embryonal nature of the tumor." (PMID 34685577, 2021). "The MnIOMCP shows both T1-weighted and T2-weighted MR contrast abilities, reasonable photothermal conversion efficiency under 808 nm NIR laser irradiation, and the strong tumor-targeting and inhibition of cancer cell growth by the interactions of MCP with overexpressed CXCR4 in the tumor." (PMID 34072160, 2021). "Furthermore, overexpression of CXCR4 in tumor tissues was shown to correlate with tumor aggressiveness and elevated risks of metastasis and recurrence." (PMID 34500609, 2021). "Finally, we constructed a tumor xenograft model by injection of Huh7 cells after CXCR4 overexpression or combined with c‐Met knockdown to verify the impact of CXCR4 on tumor growth in HCC." (PMID 34555268, 2021). "Our data show that CXCR4 also plays a role in controlling B cell survival under hypoxic conditions, suggesting that CXCR4 could be a pivotal molecule regulating B cells in the tumor microenvironment." (PMID 33771976, 2021). "The CXCR7-mediated pro-metastatic responses may depend on CXCL11 or on higher receptors availability such as ER, EGFR or CXCR4 that significantly contribute to tumor growth and metastasis." (PMID 33937018, 2021). "Thus, we argue that the CXCL12/CXCR4 axis activates immunosurveillance via a mechanism (which we name Immunogenic Surrender) that allows tumor identification by innate cells and tumor‐specific T‐cell priming." (PMID 33956406, 2021). "Additionally, CXCR4/CXCL12 are responsible for the homing of endothelial progenitor cells to the tumor bed and thus for initiating vasculogenesis." (PMID 34203660, 2021).
tumor (continued). "In a recent model of cancer cell dissemination, the chemotactic migration of CXCR4+ macrophages with their partnering MENAINV+ tumor cells, has been rendered as the possible driving force for the observed streaming migratory behavior within dissemination trajectories." (PMID 33927723, 2021). "Collectively, the results indicated that CXCL12/CXCR4 might promote PNI by provoking the tumour cell to differentiate towards Schwann‐like cell through Twist/S100A4 axis in SACC." (PMID 34170080, 2021). "Furthermore, the CXCL12/CXCR4 axis has been implicated in local tumor-supporting effects: experiments with NB cell lines and an orthotopic NB mouse model revealed a CXCL12-dependent beneficial effect of CXCR4 on tumor growth and -survival." (PMID 33287630, 2021). "Multiple tumor cell rely on CXCR4 and its ligand, SDF-1/CXCL12, to metastasis." (PMID 34220311, 2021). "Moreover, the average expression of CXCR4 was significantly elevated on total circulating neutrophils in tumor-bearing mice compared with total circulating neutrophils in healthy controls." (PMID 34876407, 2021). "Our analysis supports an association between tumor progression and CXCR4 expression in NSCLC, but does not address causality." (PMID 33507926, 2021). "The activation of CXCL12/CXCR4 might accelerate PNI through enhancing the initiation of EMT to induce tumour cells develop into Schwann‐like cells, triggering cytoskeletal rearrangement, thus acquiring a promotional migrated and invasive ability in SACC." (PMID 34170080, 2021). "The previous study indicated that FL cells having cancer stem cell-like activities interacted with FDCs in a CXCL12/CXCR4 dependent manner, including resistance to cyclophosphamide or doxorubicin, in vitro and in NOD/Scid mice and that a specific CXCL12/CXCR4 inhibitor exhibited tumor growth." (PMID 34069564, 2021). "Indeed, pharmacological inhibition of the CXCL12/CXCR4 pathway alleviates the tumor microenvironment from the lymphocyte exclusion phenotype." (PMID 33927723, 2021). "To investigate the mechanism underlying the superior abilities of tumour initiation, formation, invasion and metastasis of the ALDH+ CD44+ CXCR4+ CD24+ subpopulation, we performed microarray analysis to identify the DEGs between the ALDH+ CD44+ CXCR4+ CD24+- and ALDH− CD44− CXCR4− CD24−-PCa cells." (PMID 34247196, 2021). "Several studies have shown that the CXCR4/CXCL12 interaction may foster local tumor growth and metastatic potential by maintaining an immune-quiescent microenvironment, which could be blocked by CXCR4 antagonism." (PMID 34722241, 2021). "Additionally, LY2624587 antibody was capable of inhibiting tumor growth in a CCRF-CEM T-ALL xenograft model by preventing CXCR4 signaling." (PMID 33081391, 2020). "Although CXCR4 plays a significant role in tumor growth, angiogenesis, invasion and metastasis, long-term blockade of CXCR4 might yield severe adverse effects relating to prenatal death in mice lacking CXCL12, as it may spare the normal tissues." (PMID 33129326, 2020). "Finally, delivery of an oncolytic virus containing an antagonist of C-X-C motif chemokine receptor 4 (CXCR4) alters the tumor microenvironment with decreased Treg cells and increased proportion of immunostimulatory macrophages." (PMID 32983125, 2020). "However, the pro-tumour effect of Cxcr4 signalling at the preneoplastic stage was macrophage specific." (PMID 32325966, 2020). "Tumor cells expressing CXCR4 may be attracted toward blood vessels by perivascular fibroblasts that express CXCL12 via synergizing with CXCR4-expressing TAMs." (PMID 32943996, 2020). "In addition, CXCL12 attracts immunosuppressive innate immune cells, mostly Ly6Clow monocytes and Ly6G+ neutrophils which predominantly express CXCR4 in the tumor microenvironment." (PMID 33096815, 2020).
tumor (continued). "Moreover, we also found that elevated circ_0020710 was correlated with cytotoxic lymphocyte exhaustion, and a combination of AMD3100 (the CXCL12/CXCR4 axis inhibitor) and anti-PD-1 significantly attenuated tumor growth." (PMID 32381016, 2020). "SWIR imaging at 24-h and 36-h time points indicated differential localization of nanoprobes based on their distinct SWIR emissions, with increased accumulation of CAV1 targeted nanoprobes in the 4175TR tumor, and increased accumulation of CXCR4 targeted nanoprobes in the MCF7 tumor." (PMID 33172421, 2020). "However, it has also been shown that exosomes released from MSCs transfer mRNA encoding CXCR4, VEGF, α-SMA, and MDM2 to tumor cells, thus enhancing angiogenic activity and tumor growth." (PMID 32499786, 2020). "CXCR4 is enriched in tip cells and highly expressed in tumor vessels." (PMID 31690961, 2020). "First, poly(lactone‐co‐β‐amino ester) nanoparticles that are capable of efficient gene delivery are synthesized and are engineered for targeted delivery to BCBM through surface conjugation of AMD3100, which interacts with CXCR4 enriched in the tumor microenvironment." (PMID 32154067, 2020). "CXCR4, which is upregulated during BC progression, interacts with CXCL12 in cancer cells to mediate tumour chemotaxis and invasion through connective tissue, suggesting that CXCR4 may be a potential target for attenuation of BC metastasis." (PMID 32228629, 2020). "As a result of increased CXCR4 expression, the metastasis of tumor cells is also increased." (PMID 32486408, 2020). "Interestingly, it has been recently reported that the novel anti-CXCR4 antibody ulocuplumab shows an anti-LPL/WM activity by inhibiting tumor growth both in in vitro and in vivo studies." (PMID 32260318, 2020). "Furthermore, the SDF-1/CXCR4 axis plays an important role in the homing of MSCs for tumor cell diffusion and metastasis." (PMID 32850457, 2020). "Based on the presented findings, we may conclude that serum CXCR4 is a better candidate for a tumor marker than CXCR2 in the diagnosis of PC, while serum CXCR2 is a significant predictor of PC risk." (PMID 32867211, 2020). "In particular, ss ArtIBs formed by Ca+2 were more efficient than ArtIBs (Zn+2 50:1) in maintaining a faster and progressive protein release from the SC injection site leading to a higher accumulation and longer residence time (starting at day 3 and at least until day 10) in the remote CXCR4+ tumor." (PMID 32042562, 2020). "Interestingly, also CXCR4 inhibition results effective in reverting tolerogenic polarization of tumor microenvironment and in restoring sensitivity to CTLA-4 and PD-1 checkpoints inhibitors." (PMID 33123122, 2020). "C-X-C chemokine receptor type 4 (CXCR4) is a receptor of SDF-1α, and the binding of SDF-1α to CXCR4 modulates downstream signaling pathways, resulting in a variety of responses, such as chemotaxis, tumor cell proliferation, distant metastasis, and gene transcription." (PMID 32344892, 2020). "The enhanced CXCL12 secretion by the hypoxic tumor may lead to the recruitment of CXCR4 expressing bone marrow derived immune cells in order to restore the vasculature of the tumor after radiotherapy." (PMID 31802362, 2020). "Functionalization of ReANCs with the small molecule AMD3100, an antagonist of tumor-expressed C-X-C chemokine receptor type 4 (CXCR4), showed higher retention in CXCR4-positive tumors, allowing for detection of sub-tissue microlesions as small as 18.9 mm3 and about 1 cm deep." (PMID 33134314, 2020). "However, the roles of CXCR4 in mediating tumor-stroma networks that promoted breast malignancy were put to question in several other studies." (PMID 32582148, 2020). "Even in the sham-irradiated control group, the basal expression of CXCR4 in the tumor could be detected." (PMID 31802362, 2020). "Further studies comparing primary MSI and MSS tumors will be needed to determine whether CXCR4 expression levels differ between these tumor types." (PMID 32110952, 2020).
tumor (continued). "Previous studies indicated that CXCR4 overexpression could protect tumor cells from chemotherapy drugs." (PMID 32306562, 2020). "In addition to its value for non-invasive detection of CXCR4 expressing tumor cells, [68Ga]PentixaFor-PET has also gained considerable attention in inflammation imaging, in particular in cardiovascular disease." (PMID 32724470, 2020). "The threefold difference in the tumor absorbed doses between 211At-CXCR4 mAb and 125I-CXCR4 mAb may be explained by the difference in the weights of the tumors." (PMID 32321944, 2020). "LASP1 was previously found to be necessary for CXCR4-dependent tumor cell invasion." (PMID 32872485, 2020). "The mechanism by which LASP1 facilitates this invasive ability of tumor cells when CXCR4 is activated is unknown." (PMID 32872485, 2020). "We further investigated the potential downstream pathways that might be responsible for the repressive effect of anti-miR-21 + sh-CXCR4 on tumor progression." (PMID 33123586, 2020). "This increase in CXCR4 density in the tumor could be due to treatment-induced increase in the secretion of CXCL12 by stromal cells." (PMID 31802362, 2020). "Furthermore, CXCL12/CXCR4 axis supports fibrotic tumor microenvironment and prevents therapeutic effects of immune checkpoint blockers." (PMID 33096815, 2020). "In addition, CXCL12/CXCR4 is involved in vessel co-option and trafficking of leukocytes to the tumor." (PMID 31690961, 2020). "Furthermore, the functional blockade of CXCR4 in tumor cells is sufficient to prevent the immunosuppressive ability of MICs by restoring T cell proliferation and IFNγ expression, as well as partially preventing TAM polarization." (PMID 33123122, 2020). "The results indicated that the tumor-induced osteoclastogenesis and activation of p65 in bone tissues as well as the expression of PTHrP and CXCR4 in tumor cells were all suppressed after BSA-Au clusters treatment, which was consistent with the results detected in vitro." (PMID 32226538, 2020). "This study demonstrates the feasibility of N-[11C]methyl-AMD3465 PET imaging to monitor treatment-induced changes in the density of CXCR4 receptors in tumors and justifies further evaluation of CXCR4 as a potential imaging biomarker for evaluation of anti-tumor therapies." (PMID 31802362, 2020). "Indeed, ACKR3 can inhibit tumor growth and progression by acting on chemokine bioavailability, or it can promote tumorigenesis by regulating the CXCR4 signaling." (PMID 33066172, 2020). "Bevacizumab targeting to the SNPs of rs228014 of CXCR4, exerting anti-tumor effect." (PMID 32788609, 2020). "Its suitability for non-invasive high-contrast imaging of CXCR4 overexpressing cancers has been initially demonstrated for hematological malignancies 12, 15-18, but has also been successfully extended towards other tumor entities 19-27." (PMID 32724470, 2020). "It has been reported that cytokines and pro-inflammatory TME promote the phosphorylation of NF-κB and the expression of proliferative (cyclin D1), metastatic (MMP-9, CXCR4) tumor-promoting proteins and inhibit apoptosis (caspase-3), which have a p65-NF-κB binding site in their promoters." (PMID 32708030, 2020). "CXCR4+MET+CD44+ cells amounted to 2.2% of total tumor cells on average (range: 0.2–11%)." (PMID 32066735, 2020). "This considered, the present review is focused on the cellular events or molecular pathways which make HIV-protease inhibitors, HIV-reverse transcriptase inhibitors or CXCR4 antagonists capable of impairing the formation of new vessels that accompanies and favors tumor progression." (PMID 32528888, 2020). "Moreover, the CXCL12/CXCR4 signaling pathway promotes MDSCs trafficking in the tumor microenvironment." (PMID 33123472, 2020). "Furthermore, it was found that inhibition of HIF-1α expression and inhibition of CXCL12/CXCR4 signals all alleviate tumor cell migration and invasion." (PMID 32848510, 2020).
tumor (continued). "The molecular characterization of CTCs showed that the expression of osteotropic markers such as RANK and CXCR4 could be responsible for tumor cell homing to the bone." (PMID 32582538, 2020). "This hypothesis was supported by animal studies, showing that CXCR4-positive tumor cells migrated from their primary region to these CXCL12 secreting organs." (PMID 31802362, 2020). "In addition, CXCR4 is an effective target for improving tumor sensitivity in GBM in conjunction with radiation therapy." (PMID 33329750, 2020). "Thus, CXCL-12 signaling by receptor CXCR-4 requires an intimate interaction between CAFs and tumor cells, which would result in the proliferation of tumor cells as well as acceleration of neo-angiogenesis due to the recruitment of endothelial progenitor cells." (PMID 33585565, 2020). "To address the hypothesis that the gemR phenotype was associated with tumor cell stemness, we characterized the expression of stem cell markers ALDH1, CD133, and CXCR4 in gemR tumors." (PMID 33073205, 2020). "High CXCR4 expression also correlated with lower tumor purity and TMB." (PMID 32306562, 2020). "Moreover, we found that a high CXCR4 expression in patients was correlated with a more advanced clinical stage, which is an extremely important prognostic factor for tumor progression." (PMID 32306562, 2020). "Moreover, CXCR4 levels closely correlate with tumor progression, metastasis and lower overall survival." (PMID 32784743, 2020). "This in vivo study showed that the CXCR4 inhibitor BL-8040 may have anti-tumor effects by increasing tumor infiltration of antigen-specific effector T-cells." (PMID 32079173, 2020). "In addition, CXCR4 expression correlates with the degree of tumor infiltration and promotes a more aggressive phenotype in papillary thyroid carcinoma, and is also a negative prognostic marker for response to chemotherapy in NHL." (PMID 31991604, 2020). "Moreover, cancer cells have been found to home in on tissues with high levels of CXCL12 expression and to increase their own secretion of CXCL12 to attract CXCR4-expressing stromal cells that can, in turn, assist with tumor development." (PMID 33521055, 2020). "CXCR4 has an important function in tumor metastasis, progression, and angiogenesis." (PMID 35582437, 2020). "Therefore, omeprazole inhibits tumor invasion and regulates metabolism in vivo by inhibiting CXCR4 transcription." (PMID 32443455, 2020). "Moreover, SDF-1α/CXCR4 signaling plays a key role in common malignancies and has modulated a lot of responses, such as chemotaxis, tumor cell proliferation, invasion, and metastasis." (PMID 32344892, 2020). "Because of the roles of CXCR4 in tumor progression and immune cell trafficking, CXCR4 density in the tumor may be affected by treatment, either as a result of altered CXCR4 expression by the tumor cells, or by treatment-induced infiltration of immune cells." (PMID 31802362, 2020). "The CXCR4/CXCL12 interaction is central to tumor cell homing to distant organs." (PMID 32943996, 2020). "CXCR4 is expressed in various cell types, including tumor cells." (PMID 33195200, 2020). "Activation of the CXCR1/CXCR2 pathway and the CXCR4/CXCR7 pathway is associated with tumor aggressiveness and poor prognosis; the CXCR3 and CXCR5 axes play a role in tumor suppression; and common variants encoding the CXC chemokine gene have also been studied as biomarkers of CRC." (PMID 32774427, 2020). "Immunohistochemical staining was performed to detect the expression of CXCR4 in tumor tissues." (PMID 31949484, 2020). "As a result, [177Lu]DOTA-r-a-ABA-CPCR4 has emerged from this study as a powerful second-generation therapeutic CXCR4 ligand with greatly improved targeting efficiency and tumor retention and will be further evaluated in preclinical and clinical CXCR4-targeted dosimetry and RLT studies." (PMID 32724470, 2020). "FACS revealed a distinct population of CXCR4+MET+ cells in patient’s tumor which could be further sorted into CD44+ and CD44− cells." (PMID 32066735, 2020).